MAGEB5 (MAGE family member B5)
Synonyms: CT3.3; MAGE-B5
Tractability: No criterion of Open Targets' tractability assessment is met for any kind of drug.
Gene: Protein-coding gene on chromosome X (26,216,169 to 26,218,270, forward strand). Ensembl gene ENSG00000188408.
Gene Ontology:
Biological process: negative regulation of transcription by RNA polymerase II
Cellular component: nucleus; cytoplasm
Homologues: Orthologues: macaque MAGEB5 (76% identical), rat Mageb5 (45% identical), mouse Mageb5 (44% identical), mouse Mageb5b (44% identical), zebrafish ndnl2 (27% identical), Drosophila melanogaster MAGE (18% identical). Paralogues in human: MAGEB4 (51% identical), MAGEB3 (50% identical), MAGEB1 (47% identical), MAGEB10 (45% identical), MAGEB18 (44% identical), MAGEB16 (44% identical), MAGEB17 (44% identical), MAGEB2 (44% identical), MAGEB6 (43% identical), MAGEB6B (42% identical), MAGEA10 (41% identical), MAGEA1 (38% identical), and 25 more.
Diseases named in the same sentence as MAGEB5 in open-access papers:
MAGEB5 is named in the same sentence as 9 diseases in open-access papers, as found by Europe PMC text mining. Sharing a sentence is not in itself a finding about the gene and the disease. The quoted sentences say what the papers report.
male infertility (2 papers, 2018 to 2022). The inability of the male to effect fertilization of an ovum after a specified period of unprotected intercourse. "Our findings also show that a reduced gene expression level of the 4930567H17Rik and Mageb5 gene families, via deletion of a single palindrome arm, does not result in spermatogenic defects or male infertility." (PMID 29895860, 2018).
cancer (1 paper, 2021). A tumor composed of atypical neoplastic, often pleomorphic cells that invade other tissues. "Further analysis of the expression and genomic interaction of identified epitope peptides between HHLA2 and MAGEB5 in relation to specific immune variants provides a good basis of therapeutic approaches to inhibit this reaction and prevent viral effects related to chronic diseases and cancers." (PMID 34320928, 2021). "This study is a follow up from a previously published work on expression patterns of MAGEB5 and HHLA2 transcripts across viral and cancer associated samples, whose genetic co-expression patterns suggests viral disease and cancer causation." (PMID 34320928, 2021). "The observed co-expression pattern between HHLA and MAGEB5 as demonstrated by our previous article and this one, are the first to show co-expression and co-regulated patterns which can occur independently in viral and cancer diseases and also in viral related cancer diseases." (PMID 34320928, 2021). "The expression of Melanoma associated antigens (MAGE) have also been shown to be highly expressed in TNBC but co-expression of HHLA2 and MAGE related genes especially MAGEB5 have not been demonstrated in any cancer type." (PMID 34320928, 2021). "From the previous work on virus and cancer data we observed the expression pattern for HHLA2 and MAGEB5 across all samples suggesting that they could co-express and co-function together." (PMID 34320928, 2021).
tumor (1 paper, 2021). "HHLA2 and MAGEB5 have been individually shown to be expressed in various tumor types and the former has been associated with viral related diseases." (PMID 34320928, 2021). "MAGEB5 and MAGEB6 have been identified in different tumor types and the activation of these genes stems from the demethylation of their relative promoter regions." (PMID 34320928, 2021).
MAGEB5 also shares sentences with these, for which no sentence is quoted: breast carcinoma (1 paper); carcinosarcoma (1); colon cancer (1); epithelial neoplasm (1); mesenchymal neoplasms (1); viral diseases (1).